Y_RNA (Y RNA )
Gene: Miscellaneous RNA gene on chromosome 15 (51,884,556 to 51,884,653, forward strand). Ensembl gene ENSG00000207484.
Homologues: Orthologues: chimpanzee Y_RNA (100% identical), macaque Y_RNA (95% identical). Paralogues in human: Y_RNA (95% identical), RNY3 (94% identical), Y_RNA (94% identical), Y_RNA (93% identical), Y_RNA (92% identical), RNY3P1 (91% identical), Y_RNA (91% identical), RNY3P16 (90% identical), Y_RNA (90% identical), Y_RNA (89% identical), RNY3P14 (88% identical), RNY3P2 (88% identical), and 98 more.